RORC (RAR related orphan receptor C)
Diseases named in the same sentence as RORC in open-access papers (continued):
Sharing a sentence is not in itself a finding about the gene and the disease.
tumor (continued). "The correlations of RORC expression with tumor microenvironment factors were further assessed, including immune cell infiltration (obtained by CIBERSORT) and immunomodulators (in pancancer datasets from the Tumor-Immune System Interactions and Drug Bank [TISIDB] database)." (PMID 36186454, 2022). "The associations between the tumor purity and these 12 immune-survival-related genes were analyzed; the results revealed that four genes, i.e., FAM134B, ALDH3A2, SAV1, and RORC were positively related to tumor purity, and one gene (FN1) was negatively related to tumor purity." (PMID 35893817, 2022). "Similarly, a previous study reported that RORC expression in BLCA decreases with increasing tumor stage." (PMID 36186454, 2022). "With respect to the identification of tumor-infiltrating RORC-Tregs, additional evidence for this supposition is that the relationship between levels of the identified infiltrating RORC-Tregs and patient outcome is consistent utilizing data drawn from four different GBM transcriptome databases." (PMID 34681642, 2021). "Additionally, the expression of retinoic acid-related orphan receptor C (RORC), which functions as a DNA-binding transcription factor, was downregulated in tumour tissues from BC patients." (PMID 33805295, 2021). "Lower RORC expression was found in advanced tumours and those resistant to chemotherapy." (PMID 33805295, 2021). "In the Th17 lineage, RORC (receptor) is upregulated on the tumor infiltrating CD4+ T-cells and its ligands (CYP51A1, FDFT1, HSD17B7, LBR, TM7SF2, MSMO1, NSDHL) are also upregulated on the tumor cells, implying GBM expresses ligands that induces Th17 phenotype in tumor infiltrating helper T-cell." (PMID 34012510, 2021). "Finally, RAR-related orphan receptor C (Rorc) brain mRNA displayed a unique pattern dependent upon tumor treatment, with tumors decreasing expression during the light phase and tumor resection increasing expression during the dark phase." (PMID 31019214, 2019). "The results of our study showed that the expression of RORC declined during tumor progression." (PMID 29299026, 2017). "However, the exact role of RORC in other cancers remains unknown, although comprehensive studies of differences in RORC expression between tumor and normal tissues have revealed its potential value in CIT for a variety of cancer types." (PMID 36186454, 2022). "Several immune-related genes were shared across tumor types, with seven genes (CASP3, F2RL1, CD22, RORC, PLA2G6, SYCP1, MAP3K5) common to all four histologies." (PMID 40621458, 2025). "Dianzani C and others found that ICOS-Fc treatment inhibited tumor cell migration to the lungs in mice, increasing IL-17A and RAR-related orphan receptor C (RORc) expression while reducing IL-10 and Foxp3 expression." (PMID 39104717, 2024). "When stratifying for tumour grade, 17 genes were found to have a significant effect survival, of which four core-clock genes (BMAL1/2, CRY2 and RORC)." (PMID 37400829, 2023). "During tumor progression, CAPZA1, GRB2, NF2EL3, PLEKHO1, SIGLEC1, and UBE2Z were expressed at higher levels in late-stage KIRC, whereas EMX2, FUCA1, IMPA2, and RORC were expressed at higher levels in early-stage KIRC." (PMID 35127943, 2022). "Analysis of specific genes involved in CD4+ differentiation and function revealed differential methylation status of TBX21, GATA3, RORC, FOXP3, IL10 and IFNG in tumor CD4+ T-cells." (PMID 34012510, 2021). "Other immune-related genes of the nine-IRGP signature, including BTN3A3, RORC, and AGER, participate in promoting tumorigenesis, decreasing efficacy of immunotherapy, and preventing tumor immune killing through a variety of immunological mechanisms." (PMID 32211443, 2020). "Univariate analysis identified a significant correlation between SSTR2 and the response to the acute SA test, while SA treatment, RORC and DOK6 mRNA levels were correlated with tumor size." (PMID 23825587, 2013).
tumor (continued). "Thus, attenuated RORC expression was correlated with a blunted tumor size- and IGF-1 reduction in patients treated with SA, indicating that these analogs may adversely affect clinical recovery in the presence of EMT progression (i.e., low E-cadherin) involving RORC-mediated mechanisms." (PMID 23825587, 2013). "Additionally, RORC regulates cell proliferation and chemotherapy resistance through the PD-L1/ITGB6/STAT3 signaling axis, highlighting its role in tumor progression and therapeutic resistance." (PMID 40806474, 2025). "We also found that RORC expression was not sex-specific in most cancers, and RORC expression varied with tumor stage in some cancers." (PMID 36186454, 2022). "The elevated expressions of FAM134B; ALDH3A2; RORC; and SAV1 were related to superior MESO’s OS, indicating that only four tumor antigens could be assumed to stimulate the immune system." (PMID 35893817, 2022). "According to these results, the expression levels of NR3C2, KLF4, CASZ1, FOXD2, ATOH1, and RORC reduce in CRC and may function as tumor suppressors." (PMID 36344988, 2022). "Our in silico analysis identified tumor steroidogenesis as a means for GBM to acquire an immunosuppressive phenotype, with the generation of androgens appearing to drive RORC-Treg infiltration and the generation of estrogen driving infiltration/activation of MDSCs/TAMs." (PMID 34681642, 2021). "The analysis further revealed a total of tumor antigens including FAM134B, ALDH3A2, SAV1, RORC, and FN1, which were considered as significant candidates for the MESO-mRNA vaccine that could have immune provocative effects and be both presented and processed by APCs for a tumor response induction." (PMID 35893817, 2022). "The tumor-infiltrating RORC-Tregs we have shown to be linked to poor patient outcomes and associated with tumor androgenesis were selected based on elevated levels of FOXP3, CTLA4, GITR, RORC and GATA3 transcripts in the whole tumor, not from individual T-cells." (PMID 34681642, 2021). "RORc was not expressed in the control tissues, while weakly distributed in the tumor cells of LSCC." (PMID 34941188, 2021). "For example, RORC agonists combined with the checkpoint inhibitor anti-CTLA-4 could enhance Th17 cell differentiation, migration, and infiltration, inhibit Treg cell production, increase the function of anti-tumor effector T cells, and inhibit the growth of MC38 COAD cells." (PMID 39252305, 2024). "The results showed that, in the TCGA cohort, C12orf56 and RORC had higher expression in normal samples, while EREG, INHBB, MAGEA12, and MMP10 had higher expression in tumor samples; ASRGL1 showed no expression difference between normal and tumor samples." (PMID 39883700, 2025). "Reportage of tumor RORC-Treg infiltration was calculated from the averaged, normalized levels of FOXP3, CTLA4, GITR, RORC and GATA3." (PMID 34681642, 2021).
cancer (29 papers, 2018 to 2026). A tumor composed of atypical neoplastic, often pleomorphic cells that invade other tissues. "RORC was associated with a variety of biological processes and signal transduction pathways in various cancers." (PMID 36186454, 2022). "To explore the mechanisms underlying differential RORC expression in various cancers, we explored the RORC mutation rate in multiple cancer types in the TCGA database using TIMER2.0 and DriverDBv3." (PMID 36186454, 2022). "We also explored the associations between RORC expression and clinical features in 33 human cancers." (PMID 36186454, 2022). "The data herein strongly support the view that the main Treg subtype supporting GBM ferocity is the RORC-Treg class, a class of Tregs normally associated with mucin-rich cancers such as colorectal and pancreatic." (PMID 34681642, 2021). "Regarding the correlations between RORC expression and MHC molecules (which are closely associated with cancer occurrence and development), RORC expression exhibited the strongest positive correlation with HLA-F in ACC, and the strongest negative correlation with B2M in UVM." (PMID 36186454, 2022). "Interestingly, abnormal RORC methylation occurred in the majority of cancers with differential RORC expression, which indicates that differential RORC expression may be caused by abnormal methylation in some cancers." (PMID 36186454, 2022). "Expression of RORC was found to be significantly decreased in several types of cancer cells, indicating a probable regulatory role of RORC in tumorigenesis." (PMID 40534841, 2025). "Deregulation expression of NUMBL and RORC have been reported to be involved in the regulation of cancer cell migration, invasion, and metastasis." (PMID 37373553, 2023). "This study comprehensively demonstrates the important role that RORC plays in immunity in many cancers." (PMID 36186454, 2022). "In conclusion, RORC expression can be an important regulator of cancers and RORC has prognostic value in some cancers." (PMID 36186454, 2022). "For many cancers, Th17-cell signatures (RORC, IL17, IL23, STAT3) are correlated with the worse clinical outcomes." (PMID 34781983, 2021). "Additionally, overexpression of RORC sensitizes cancer cells to cisplatin chemotherapy and augments the apoptotic response pathway." (PMID 39518891, 2024). "As for gene RORC, its agonists were considered to have great anti-cancer potential." (PMID 39252305, 2024). "In short, RORC is an important gene in the immune microenvironment in cancer patients." (PMID 36186454, 2022). "Interestingly, the biological processes involving RORC (according to GSEA) differed among these five cancers." (PMID 36186454, 2022). "We also investigated the biological processes and signaling pathways involving RORC in cancers." (PMID 36186454, 2022). "RORC is a member of the nuclear orphan receptor family and performs critical regulatory functions in cell growth, metastasis, chemoresistance, and the negative regulation of PD-L1 expression in various cancers." (PMID 35893817, 2022). "Furthermore, RORC, a core-clock component, acts as a transcription factor, and regulates various cancer-related processes such as cell proliferation, immune cell infiltration, and expression of immunomodulators, thereby influencing the formation of metastatic niches." (PMID 40382284, 2025). "Interestingly, RORC expression was not significantly correlated with MSI in most cancers, but was negatively associated with MSI in TGCT, LUSC, and HNSC." (PMID 36186454, 2022). "The exact role that RORC plays in other cancers is still unknown." (PMID 36186454, 2022). "Therefore, the authors propose that ASCP evolves from the same lineage as PDAC but consists of enriched levels of RORC-positive cancer stem cells which may drive other tumors with adenosquamous features." (PMID 36010939, 2022). "Notably, RORC expression had prognostic value in some cancers, especially KIRC, LGG, and MESO." (PMID 36186454, 2022).
cancer (continued). "Among 7912 samples across 18 cancer types, we interestingly observed that the majority of the clock control gene, such as HLF, KLF10, FBXL3, TEF, RORs (RORA, RORB, RORC), and NR1D2, are down-regulated in a wide range of cancers." (PMID 36895015, 2023). "We found that the significantly activated regulons were involved in T cell biology (RORC, TCF7, NFATC1, and LEF1) or disease pathogenesis (IKZF2 for CD30+ TMF and BATF3 for cALCL) or reported cancer biology (POUZAF1 and TSHZ2)." (PMID 37790936, 2023). "ARNTL2 was one of the most amplified genes found in 16 cancers, followed by RORC in 14 cancers and NR1D1 and CRY1 in 12 cancers each." (PMID 31014368, 2019). "In order to achieve a systematic understanding of circadian clock in cancer, we define a core subset of clock family genes including 7 positive regulators (CLOCK, NPAS2, ARNTL, ARNTL2, RORA, RORB, and RORC) and 7 negative regulators (PER1, PER2, PER3, CRY1, CRY2, NR1D1, and NR1D2)." (PMID 31708917, 2019). "Over-expression of RORC resulting CD4 + T cells polarizing into Th17 cells, while Th17 cells were plastic, environmental factors could determine that Th17 cells transformed intopro- or anti-cancer phenotype." (PMID 39252305, 2024). "However, RORC was amplified in two cancers, ESCA and KIRC, which was not coincident with transcriptional alterations." (PMID 33842355, 2021). "With the exception of three clusters of NRs representing NR classes I (cluster I: RORC, VDR, PPARA, NR1D1, THRA, RORA, NR1H3; cluster II: RARB, PPARG, THRB) and III (cluster III: ESR1, PGR, AR, ESRRG), NR class was not a good determinate of NR expression patterns in the different cancer types." (PMID 32024906, 2020). "In addition, the copy number variations investigation revealed that RORC and CSNK1D genes showed widespread copy number amplification across various cancer types whereas almost no CNV was detected in THCA, KIRC, and KIRP." (PMID 36895015, 2023).
infection (11 papers, 2016 to 2025). The state of being infected such as from the introduction of a foreign agent such as serum, vaccine, antigenic substance or organism. "Indeed, transcriptome analyses revealed increased expression of proinflammatory IL17A, IL17F, and RORC (which encodes the IL-17 transcription factor RORγt38) genes in rAAV-IL-27p28-treated mice early during infection." (PMID 36028492, 2022). "In addition, the Th17 signature cytokine IL-17A and its master transcription factor, RORc, were also found to be elevated in early phase of infection." (PMID 35014610, 2022). "From the transcriptomic analysis of bovine immune cells (PBMCs), it was suggested that infection through the epithelial cells elicited prolonged Th17-derived immune response, as indicated by upregulation of IL-17A, IL-17F and RORC until 120 h p.i., compared to directly infected PBMCs." (PMID 33273606, 2020). "We found that levels of TBX2, GATA3, RORC, SPI1, and BCL6 in the livers of infected rabbits were elevated on days 5 and 15 post-infection (PI)." (PMID 37593762, 2023). "Thus the negative correlation between IP-10 and RORC in our study could be due to the biased Th1 response at the detriment of Th17 response, which has been described in pathogenic SIVmac infection in contrast to natural hosts of SIVs." (PMID 27509048, 2016). "The transcription of RORC was not affected by infection with HIV." (PMID 29091911, 2017).
lung (1 paper, 2019). "Interestingly, RORC was also previously found in a 3-gene signature to distinguish lung ADC and lung SCC." (PMID 30532070, 2019).
RORC also shares sentences with these, for which no sentence is quoted: type 2 diabetes (3 papers); Allergy (2); candidiasis (2); diabetes (2); melanoma (2); alcoholic hepatitis (1); allergic asthma (1); amyotrophic lateral sclerosis (1); arthropathy (1); atopic dermatitis (1); autoimmune uveitis (1); cerebellar ataxia (1); chronic sinusitis (1); colon adenocarcinoma (1); esophageal adenocarcinoma (1); experimental autoimmune encephalomyelitis (1); food allergies (1); gastritis (1); Glucose intolerance (1); Granuloma (1); hepatic (1); Hypernatremia (1); Hypertension (1); immune thrombocytopenia (1); Immunodeficiency (1); infectious disease (1); inflammation (1); intestinal inflammation (1); leukopenia (1); liver cancer (1).
A further 15 diseases each share a sentence with RORC in 1 paper.